WNT16 (Wnt family member 16)
Diseases named in the same sentence as WNT16 in open-access papers (continued):
Sharing a sentence is not in itself a finding about the gene and the disease.
WNT16 also shares sentences with these, for which no sentence is quoted: colon cancer (2 papers); colorectal (2); lupus (2); melanoma (2); neurodegenerative disease (2); Alzheimer disease (1); Arthritis (1); autism spectrum disorder (1); cardiac hypertrophy (1); Coffin-Siris syndrome (1); colitis (1); erectile dysfunction (1); idiopathic scoliosis (1); osteogenesis imperfecta (1); Parkinson disease (1); periodontitis (1); psoriatic arthritis (1); skeletal diseases (1); type 1 diabetes mellitus (1); Uterine leiomyoma (1); viral infection (1).